HYAL2 (hyaluronidase 2)
Description:
Catalyzes hyaluronan degradation into small fragments that are endocytosed and degraded in lysosomes by HYAL1 and exoglycosidases. Essential for the breakdown of extracellular matrix hyaluronan.
Synonyms: LuCa-2; LUCA2; MCCS
Tractability: Antibody: UniProt places it where antibodies can reach, with high confidence; its Gene Ontology location is reachable by antibodies, with high confidence; UniProt predicts a signal peptide or a membrane-spanning region. PROTAC: ubiquitination databases record sites on it.
Gene: Protein-coding gene on chromosome 3 (50,315,845 to 50,324,687, reverse strand). Ensembl gene ENSG00000068001.
Subcellular location: Cell membrane
Pathways (Reactome):
Metabolism: Hyaluronan degradation; Hyaluronan metabolism
Gene Ontology:
Molecular function: enzyme binding; hyaluronic acid binding; hyaluronoglucuronidase activity; hyalurononglucosaminidase activity; protein binding; receptor signaling protein tyrosine kinase inhibitor activity; receptor tyrosine kinase binding; virus receptor activity; transforming growth factor beta binding; transcription coactivator activity
Biological process: cartilage development; cellular response to fibroblast growth factor stimulus; cellular response to interleukin-1; cellular response to transforming growth factor beta stimulus; cellular response to tumor necrosis factor; cellular response to UV-B; glycosaminoglycan catabolic process; hyaluronan catabolic process; monocyte activation; negative regulation of cell growth; negative regulation of fibroblast migration; negative regulation of phosphatidylinositol 3-kinase/protein kinase B signal transduction; positive regulation of inflammatory response; positive regulation of interleukin-6 production; positive regulation of interleukin-8 production; response to antibiotic; response to reactive oxygen species; response to virus; kidney development; positive regulation of extrinsic apoptotic signaling pathway; positive regulation of protein import into nucleus; positive regulation of transcription by RNA polymerase II; positive regulation of urine volume; renal water absorption; symbiont entry into host cell; and 2 more
Cellular component: apical plasma membrane; cell surface; cytoplasm; cytoplasmic vesicle; cytosol; endocytic vesicle; external side of plasma membrane; lysosome; membrane raft; microvillus; perinuclear region of cytoplasm; plasma membrane; endoplasmic reticulum; Golgi membrane; RNA polymerase II transcription regulator complex
Genetic constraint (gnomAD): Loss-of-function variants: 34 observed, 40.76 expected, observed/expected ratio (o/e) 0.83, 90% interval 0.63 to 1.11. The upper end of that interval is the gene's LOEUF score, 1.11, which puts it in group 4 of 6, group 1 being the genes least tolerant of losing a copy. Missense variants: 635 observed, 667.38 expected, observed/expected ratio (o/e) 0.95, 90% interval 0.89 to 1.02. Synonymous variants: 262 observed, 261.58 expected, observed/expected ratio (o/e) 1, 90% interval 0.9 to 1.11.
Homologues: Orthologues: chimpanzee HYAL2 (99% identical), macaque HYAL2 (98% identical), pig HYAL2 (90% identical), rabbit HYAL2 (90% identical), guinea pig HYAL2 (82% identical), mouse Hyal2 (82% identical), rat Hyal2 (82% identical), tropical clawed frog hyal2 (55% identical), zebrafish hyal2b (47% identical), zebrafish hyal2a (46% identical), Caenorhabditis elegans chhy-1 (27% identical). Paralogues in human: HYAL1 (37% identical), HYAL3 (37% identical), HYAL4 (37% identical), SPAM1 (35% identical).
Diseases named in the same sentence as HYAL2 in open-access papers:
HYAL2 is named in the same sentence as 83 diseases in open-access papers, as found by Europe PMC text mining. Sharing a sentence is not in itself a finding about the gene and the disease. The quoted sentences say what the papers report.
breast carcinoma (21 papers, 2010 to 2025). "HA is localized in both the stroma and breast carcinoma cells, while hyaluronidase 2 (HYAL2) is predominantly localized in breast carcinoma cells." (PMID 40443562, 2025). "The combined overexpression of HAS and either HYAL1 or HYAL2 is characteristic of the invasive front of human breast cancer." (PMID 37568628, 2023). "Compared with that in healthy tissue, the expression of HYAL2 was significantly decreased in endometrial cancer; in contrast, the expression in breast cancer was markedly increased, especially at the margins of invasive breast cancer." (PMID 37568202, 2023). "On the other hand, DDIT significantly reduced the expression of hyaluronidases HYAL-2, TMEM2 (encoding the main hyaluronidase expressed in this breast cancer cell line) and KIAA1199/CEMIP, while it enhanced HYAL-1 expression." (PMID 36497283, 2022). "But it is interesting that CpG_3 of HYAL2 showed the most significant correlation to PDAC, whereas CpG_4 of HYAL2 was the most significant site correlated to breast cancer." (PMID 28978057, 2017). "Recently, we have shown lower HYAL2 methylation level and higher HYAL2 gene expression in the peripheral blood of breast cancer patients compared to controls." (PMID 28978057, 2017). "By using generated polyclonal antibodies against Hyal-2, a 53-kDa protein is shown in breast cancer MCF7, neuroblastoma SK-N-SH, prostate cancer DU145, kidney fibroblast COS7 and L929 fibrosarcoma cells." (PMID 27845895, 2017). "Decreased methylation of HYAL2 has been reported in the peripheral blood DNA of breast cancer patients and head and neck cancer patients." (PMID 28978057, 2017). "In breast cancer cells, cell-surface Hyal2 has been shown to form a functional complex with CD44 and NHE1." (PMID 25716319, 2015). "In this study, we demonstrate that microvascular endothelial cells express high levels of CD44 and HYAL2 and investigated their functional roles in cotrolling the formation of vessel-like structures and dissemination of breast cancer cells." (PMID 24614402, 2014). "Interestingly, 4-MU has been shown to reduce HA synthesis and HAS2 and CD44 expression, but increases HYAL1 and HYAL2 in breast cancer cell lines, and to a greater extent in ER− cells." (PMID 37568628, 2023). "Besides this, it has been reported that HAS2 knockdown in breast cancer cells leads to a downregulation of HYAL2 and CD44." (PMID 35767191, 2022). "Whereas a physical interaction between CD44 and HYAL2 has been demonstrated in breast cancer cell line MDA-MB-231 and rat v-Src-transformed fibroblasts, we were unable to demonstrate such an interaction in TIME cells using co-immunoprecipitation (data not shown)." (PMID 24614402, 2014). "These agents include Zfra4-10 peptide, WWOX7-21 peptide, Hyal-2 antibody, pY33-WWOX antibody, and HAson, which are potent in inhibiting the growth of breast cancer cells and melanoma in vivo." (PMID 32764489, 2020). "Here, we report a distinct and selective response to estrogen among the 3p21.3 locus genes in breast cancer cells, where the HYAL1 gene was repressed as compared to HYAL2 and HYAL3, and to other genes tested within the cluster." (PMID 27764788, 2016). "Aberrant expression of HYAL1, HYAL2 and SPAM1 has also been reported in breast cancer, and in particular upregulation of HYAL1 was observed in infiltrating invasive duct cancer tissues and metastatic lymph nodes." (PMID 27764788, 2016). "This is consistent with the finding that in breast cancer cells, Hyal-2 forms a complex with CD44 and the Na+–H+ exchanger 1 (NHE1), and HA degradation by Hyal-2 depends upon its interaction with CD44 at the membrane surface." (PMID 24653726, 2014). "While the direct link between HYAL2 and prostate cancer is not explicitly detailed, the evidence supports HYAL2 role in the progression of some cancers such as bladder and breast cancer." (PMID 40567905, 2025).
breast carcinoma (continued). "This negative regulation of HYAL1 by ERα provides a mechanism supporting the specific inverse correlation we found between ESR1 and HYAL1, but not with HYAL2 or HYAL3 in the METABRIC cohort consisting of 1980 cases of breast cancer." (PMID 27764788, 2016).
lung carcinoma (7 papers, 2004 to 2024). "The correlation coefficient according to Spearmen's rank test between HYAL1 and HYAL2 mRNA level was 0.67 (P = 0.005) in lung cancer samples (i.e statistically valid)." (PMID 18725949, 2008). "However, HYAL2 mutations were not identified in 40 lung cancer cell lines and overexpression of HYAL2 in 4 chromosome 3p-deficient lung cancer cell lines did not alter cell proliferation or apoptosis rates." (PMID 39056785, 2024). "The human hyaluronidase genes on chromosome 3p21.3 were first identified in a 630 kbp interval that was frequently deleted in LUng Cancer as LUCA1 (HYAL1), LUCA2 (HYAL2) and LUCA3 (HYAL3)." (PMID 39056785, 2024). "The HYAL2 protein was identified as a receptor for the sheep lung cancer retrovirus, JSRV, and a sequestration mechanism inactivating HYAL2 protein was demonstrated." (PMID 18725949, 2008). "Since we demonstrated tumour suppressor function of HYAL1 and HYAL2 in SCID mice, we suggested that in primary renal and lung cancers expression of these genes might also be distorted." (PMID 18725949, 2008). "Expression of HYAL1 and HYAL2 was almost undetectable in the KRC/Y renal and U2020 lung carcinoma lines (data not shown), which were used in our growth suppression experiments for testing RASSF1A and G21/NPRL2." (PMID 18725949, 2008). "Deletions in HYAL2 and FHIT, present in lung tumors, have been shown to be significantly concordant with deletions in paired sputum samples and significantly higher in patients with lung cancer compared to smokers without lung cancer." (PMID 24840047, 2014).
melanoma (6 papers, 2013 to 2025). A malignant, usually aggressive tumor composed of atypical, neoplastic melanocytes. "The reduction of hyaluronan in the tumor tissue has been shown to be due to the loss of HAS1 and HAS2, and increased HYAL2, and this associated with poor prognosis and shortened disease-specific survival in melanoma." (PMID 35127523, 2021). "This is due to the reduced expression of HAS1 and 2 and the increased expression of HYAL2 in melanoma cells." (PMID 35127523, 2021). "We have previously demonstrated that decreased expression of HAS1 and HAS2 and increased expression of hyaluronan degrading enzyme HYAL2 correlates with decreased tumoral hyaluronan content in the invasive melanomas." (PMID 27184066, 2016). "In the stroma, the intensity of HYAL2 immunoreactivity correlated negatively with hyaluronan staining intensity in superficial melanomas (correlation coefficient -0.655, p=0.040)." (PMID 23560496, 2013). "Our results suggest that the reduction of hyaluronan in the invasive melanoma is due to increased expression of hyaluronidase 2 and decreased expression of hyaluronan synthases 1–3." (PMID 23560496, 2013). "HYAL2 immunostaining localized mostly on the cytoplasm of the melanoma cells." (PMID 27184066, 2016). "Especially the staining of HYAL2 was changed in dysplastic nevi and melanomas compared to benign nevi, providing a logical explanation for the observed alterations in hyaluronan staining, but also suggesting a connection to the reduced staining of CD44 as previously reported." (PMID 23560496, 2013). "Similarly in the stromal compartment hyaluronan content is significantly decreased in melanomas compared to benign lesions, concurrent with increased activity of HYAL2 and decreased expression of hyaluronan synthases." (PMID 23560496, 2013). "The HYAL2 staining in melanocytic cells was similar in LN metastases as in melanomas." (PMID 23560496, 2013). "In addition to HAS1 and HAS2 expression, the observed HYAL2 expression may contribute to melanoma progression." (PMID 27184066, 2016). "However, higher proportion of stromal cells were HYAL2 positive (6-25%) in deep melanomas (p=0.028), and the intensity of stromal HYAL2 staining was higher in dysplastic nevi (p=0.006) and in superficial (p=0.006) and deep melanomas (p=0.010) compared to benign nevi." (PMID 23560496, 2013). "An upregulation of both HYAL2 and HAS1-2 in dysplastic nevi and in situ melanomas was also observed in the present study." (PMID 23560496, 2013). "Further studies are needed to clarify the prognostic power of HYAL2 upregulation and HAS1-3 downregulation in melanoma." (PMID 23560496, 2013). "The proportion of HYAL2 positive melanoma cells was mostly high (76–100 %, data not shown) for all stages." (PMID 27184066, 2016). "Decreased tumoral hyaluronan content is accompanied by an increase in the hyaluronan degrading enzyme, hyaluronidase 2 (HYAL2), and a decrease in HAS1 and HAS2 expression in invasive melanomas and lymph node metastases compared to benign nevi and in situ melanomas." (PMID 27184066, 2016). "HYAL2 has also been shown to directly cleave CD44, which may disturb the hyaluronan-CD44 interaction and release locally growing melanoma cells enabling the cells to spread." (PMID 27184066, 2016).
colon cancer (4 papers, 2017 to 2023). "In colon cancer patients, Pfütze and colleagues evaluated methylation status of (hyaluronoglucosaminidase 2 protein) HYAL2, a gene encoding HYAL2 with an altered expression in several cancers." (PMID 31390840, 2019). "The activity of multiple hyaluronidase isoforms (HYAL1, 2, 3, and SPAM1) is increased in colon cancer patients, and the increased HYAL1 and HYAL2 are particularly closely related to the aggressiveness of cancer." (PMID 37568202, 2023).
ovarian carcinoma (4 papers, 2009 to 2022). A malignant neoplasm originating from the surface ovarian epithelium. "The present findings of decreased HYAL1 and HYAL2 mRNA in endometrial cancer are consistent with the results we have recently shown in ovarian cancer." (PMID 20875124, 2010). "Lower HAS2 expression and high expression of HYAL2 and HYAL3 favours the survival of ovarian cancer patients." (PMID 35767191, 2022). "We analysed a panel of four different ovarian cancer cell lines (i.e., SW 626, SKOV3, Caov-3 and PA-1) and measured the expression levels of several HA-related genes, namely HAS1-3 and HYAL2-3." (PMID 35767191, 2022). "HAS1, HYAL1 and HYAL4 mRNA expression is significantly upregulated, whereas HAS2, HYAL2 and HYAL3 mRNA expression is significantly downregulated in ovarian cancer tissue compared to controls." (PMID 35767191, 2022). "Following an evaluation of hyaluronan-related gene expression in the ATCC ovarian cancer panel, we studied SKOV3 and SW 626 ovarian cancer cells subjected to HAS2 siRNA or control siRNA treatment in terms of HAS1-3, HYAL2 and HYAL3 mRNA expression." (PMID 35767191, 2022). "At the molecular level, we evaluated basal expression levels of the HA axis in a panel of ovarian cancer cell lines and compared control ovarian cancer cells and HAS2 knockdown cells regarding gene expression of HAS1-3 and HYAL2-3, CD44, RHAMM and versican by qPCR." (PMID 35767191, 2022). "Our TNMplot analysis of over 700 ovarian cancer specimens revealed that HAS1, HYAL1 and HYAL4 mRNA expression is significantly upregulated, whereas HAS2, HYAL2 and HYAL3 mRNA expression is significantly downregulated in ovarian cancer tissue compared to controls." (PMID 35767191, 2022). "HYAL1 and HYAL2 expression was not different between the chemosensitive and chemoresistant primary ovarian cancer cells nor between CBP-resistant OV-90 cells compared to parental cells." (PMID 31443261, 2019). "Like in ovarian cancer, hyaluronidase activity in DCBCL tissue extracts was not correlated with HYAL2 expression." (PMID 19435493, 2009).
pulmonary fibrosis (4 papers, 2017 to 2025). Chronic progressive interstitial lung disorder characterized by the replacement of the lung tissue by connective tissue, leading to progressive dyspnea, respiratory failure, or right heart failure. "HYAL2 expression is elevated in both Idiopathic pulmonary fibrosis pulmonary fibrosis and pulmonary hypertension." (PMID 40646377, 2025). "In a rat model of radiation-induced lung injury, HYAL2 is involved in HA turnover during the early phase of lung injury and in the pathogenesis of pulmonary fibrosis." (PMID 40646377, 2025). "Targeting HYAL2 in the lung parenchyma and vasculature may aid in the treatment of pulmonary hypertension and pulmonary fibrosis, while anti-HYAL2 therapies may be of benefit to patients with progressive kidney disease." (PMID 33809827, 2021). "The published observations regarding HYAL2 expression in PH are mixed; whereas Hyal2 gene expression in IPAH-derived SMC was lower than donor controls, its expression was higher in the lung tissues of patients with PH stemming from idiopathic pulmonary fibrosis." (PMID 31937874, 2020).
colorectal cancer (3 papers, 2020). A primary or metastatic malignant neoplasm that affects the colon or rectum. "Even though we did not observe consistently lower or higher levels of HAS, HYAL2 or CD44 correlativity tests for colorectal cancer show a strong positive correlation between HAS, HYAL and CD44; many of them with strong statistical significance." (PMID 32610620, 2020). "In colorectal cancer, high expression of HYAL1 and HYAL2 can inhibit tumor metastasis, but in triple-negative breast cancer, high expression of HYAL2 genes is associated with shorter disease-free survival, higher tumor recurrence rate, and higher tumor metastasis rate." (PMID 33381460, 2020).
endometrial cancer (3 papers, 2010 to 2023). Primary or metastatic malignant neoplasm involving the endometrium (mucous membrane that lines the endometrial cavity). "For example, in endometrial cancer, HYAL1 and HYAL2 are downregulated compared to healthy tissue, and this phenotype correlates with the accumulation of hyaluronan." (PMID 34540372, 2021). "It is possible that in endometrial cancer the HYAL mRNA expression depends on the status of the chromosome 3p21.3 locus, and the decreased expression of HYAL1 and HYAL2 may be explained by concomitant deletions of these closely mapped genes." (PMID 20875124, 2010).
pancreatic cancer (3 papers, 2017 to 2023). "Reports substantiate high expressions of endogenous HYAL2 and HYAL3 in different pancreatic cancer cell lines including the Panc-1, and a negligibly low level of HYAL1." (PMID 33572222, 2021).
prostate carcinoma (3 papers, 2013 to 2025). A carcinoma that arises from epithelial cells of the prostate gland. "Degradation products of Hyal2 in particular have been associated with an increase in angiogenesis in the context of xenograft prostate cancer models, outside of the context of JSRV infection." (PMID 23537062, 2013). "This evidence can provide a convincing rationale for investigating HYAL2 and its contribution to prostate cancer." (PMID 40567905, 2025).
acute coronary syndrome (2 papers, 2021). Signs and symptoms related to acute ischemia of the myocardium secondary to coronary artery disease. "Acute Coronary Syndromes (ACS) with plaque erosion display dysregulated hyaluronan metabolism, with increased hyaluronidase-2 (HYAL2) expression." (PMID 33733989, 2021). "A recent clinical study revealed that the expression of HYAL2 and CD44 in peripheral blood mononuclear cells (PBMCs) increased in acute coronary syndrome (ACS), especially in patients with plaque erosion compared with stable CAD and healthy people." (PMID 33644134, 2021).
brain injuries (2 papers, 2017 to 2022). "HA protects neurons from traumatic brain injuries, and this could be related with HA-mediated disappearance of Hyal-2, which reduces the WWOX/Smad4 signaling." (PMID 27845895, 2017). "The HYAL-2/WWOX/SMAD4 complex plays a critical role in hyaluronan or TGF-β1-mediated cell proliferation or apoptosis, neuronal death during traumatic brain injury in vivo, and activation of cytotoxic HYAL-2+ CD3− CD19− Z lymphocytes in vivo." (PMID 35883580, 2022).